FAM223A (family with sequence similarity 223 member A)
Synonyms: CXorf52; LINC00204A; NCRNA00204; SPCX; NCRNA00204A
Gene: Long non-coding RNA gene on chromosome X (154,571,248 to 154,571,960, forward strand). Ensembl gene ENSG00000279245.
Homologues: Paralogues in human: FAM223B (100% identical).